ALB (albumin)
Diseases named in the same sentence as ALB in open-access papers (continued):
Sharing a sentence is not in itself a finding about the gene and the disease.
cancer (continued). "Besides BSA, other statistically significant covariates included in the model were: age, albumin on CL/F, total protein on VC/F, sex on VP/F, and cancer type on F1." (PMID 36755948, 2023). "In addition, albumin can bind to special receptors expressed in cancer cells and improve the binding and internalization of the nanoparticles." (PMID 37836018, 2023). "The FDA approved albumin nanoparticles with encapsulated PTX for cancer chemotherapy." (PMID 37836018, 2023). "The study found that the level of ALB can reflect the nutritional status of cancer patients." (PMID 37081512, 2023). "Serum albumin has been described as an independent prognosticator of survival in various cancers." (PMID 37128769, 2023). "Albumin is reported to enter cancer cells through the gp60 receptor, and the RBD of SARS‐CoV‐2 enters cells through the ACE2 receptor; therefore, we speculated that the enhanced cellular uptake may be independent of their receptors." (PMID 36684090, 2023). "Similarly, a nanocarrier based on bovine serum albumin and DNA including a pH-responsive i-motif and a cancer cell-targeted guanine-quadruplex-structured aptamer also showed accurate targeting and efficient therapeutic effect on cancer cells." (PMID 37021044, 2023). "Also, the albumin to globulin ratio (AGR) has been proposed to have a predictive value for cancer patients." (PMID 37396996, 2023). "This evidence could explain the great relevance of LDH and albumin levels in oncological emergencies as biomarkers of cancer progression and simultaneously systemic inflammatory response." (PMID 38094601, 2023). "In order to enhance the effectiveness of albumin-based nanoparticles that are used for treating different types of cancer, researchers must concentrate on comprehending and communicating the relationship between the preparation conditions and the intended therapeutic use." (PMID 37836018, 2023). "Our results indicate that appetite, along with fatigue, and the biochemical markers albumin and CRP/albumin ratio, could be considered valuable prognostic markers that may be used when assessing remaining survival time in patients with cancer." (PMID 37880704, 2023). "However, traditional nutritional parameters such as body mass index (BMI) and serum albumin (ALB) have certain limitations in estimating the nutritional status of cancer patients." (PMID 37836546, 2023). "In conclusion, in the era of transcriptomic, proteomic, and metabolomic analyses towards precision medicine in oncology, serum ALB might arise as costless and readily available predictor of cancer progression and survival." (PMID 37762957, 2023). "Notably, while serum ALB concentration usually remains in the normal range in the early stages of cancer, it has been reported to dramatically decrease as the disease progresses, thereby serving as a valuable prognostic marker." (PMID 37762957, 2023). "Furthermore, systemic inflammatory response biomarkers such as the CRP-to-albumin ratio and the Prognostic Nutrition Index are also known to have prognostic value in cancer." (PMID 36674837, 2023). "However, further research is needed to elucidate the precise mechanisms by which albumin impacts cancer prognosis in humans." (PMID 37580693, 2023). "As such, albumin levels are a well-established indicator for prognosis in various cancers." (PMID 36848404, 2023). "Another explanation could be highly proliferating cancer cells increased uptake of serum albumin through induce Albumin Binding Proteins (ABP)." (PMID 36869395, 2023). "Pro-inflammatory cytokines have an impact on albumin synthesis and could contribute to low albumin levels in situations of chronic inflammation such as cancer." (PMID 36624406, 2023).
cancer (continued). "The cells were further annotated as specific cell type subpopulations according to the expression of classic markers, including T cells (CD3D+), myeloid cells (CD68+), endothelial cells (CD34+), hepatocytes (ALB+), B cells (CD79A+), and cancer-associated fibroblasts (CAFs) (ACTA2+)." (PMID 37383234, 2023). "The globulin-to-albumin ratio (gar) is the ratio of the serum globulinlevel and the serum albumin level, it reflects the systemic inflammatory responseand has been used to predict the poor prognosis of various cancers and chronicdiseases in previous reports." (PMID 39077558, 2023). "Here, we report a series of proof-of-concept experiments using the all-dielectric metasurface biosensors for the detection of cancer markers that coexist with other actual proteins, such as albumin, IgG, and different cancer markers, thereby clarifying the robustness of metasurface biosensors." (PMID 36979589, 2023). "Amyloid nanofibers obtained from bovine serum albumin have been used as one of the most important carriers of medicinal substances in chemotherapy, including cancer, and due to their high binding capacity, they are of great interest for both hydrophilic and hydrophobic drugs." (PMID 37809783, 2023). "Decreased albumin level is a sign of poor prognosis for cancer." (PMID 38066499, 2023). "The modified Glasgow Prognostic Score (mGPS), a widely used composite score including CRP and serum ALB to estimate postoperative outcome in cancer patients, has been shown to be a predictor of mortality among patients undergoing chemotherapy for unresectable colorectal cancer." (PMID 37762957, 2023). "The PNI, which is calculated based on the serum albumin concentration and peripheral blood lymphocyte count, is a nutritional scoring tool that is used to assess the nutritional and immune status of patients with cancer." (PMID 37642856, 2023). "For instance, one might speculate that inflammation level (e.g., CRP, neutrophils, and NLR) might increase whereas albumin level might decrease following a cancer diagnosis, because of cancer biology, cancer treatment, or both." (PMID 37876941, 2023). "Both albumin and globulin could be involved in cancer progression in various ways and play crucial roles." (PMID 37491191, 2023). "Low concentration of albumin may reflect a worse nutritional status, and the undernutrition may weaken the immune system and have an adverse impact on the prognosis of cancer patients." (PMID 37334172, 2023). "LDH and albumin are generally accepted prognostic variables for survival in cancer patients and might mask the effect of NT‐proBNP with regard to long‐term survival but not with regard to the short‐term outcome of induction therapy." (PMID 36588398, 2023). "KPS, stage of cancer, and albumin showed a moderate impact on VTE." (PMID 36872336, 2023). "Additionally, another review article explores the application of serum albumin-based delivery systems as nanoprobes for cancer diagnosis and treatment." (PMID 37836018, 2023). "Applications of albumin-based hydrogels in cancer therapy (Excerpt)." (PMID 37113668, 2023). "However, this mortality difference disappeared when age, cancer, and albumin levels were adjusted in a multivariate Cox regression model (HR 0.98, CI: 0.79–1.2, p = 0.85)." (PMID 38068260, 2023). "Levels of preoperative platelets and albumin level are also related to the prognosis of cancer." (PMID 37793977, 2023). "Furthermore, albumin has been shown to be a prognostic factor and predictive marker of treatment response in many cancer types when combined with C-reactive protein (CRP), fibrinogen, globulin, and lymphocyte." (PMID 37371699, 2023). "One study found that the association of hemoglobin, albumin, lymphocyte levels, and platelets represents a good predictor for negative outcomes in patients with cancer." (PMID 36980085, 2023). "Serum albumin, a commonly used marker, examines the nutritional status of cancer patients." (PMID 37685702, 2023).
cancer (continued). "Thus, we present the albumin-based photoluminescent nanoparticles as promising photo-stable agents for expanding into functional imaging and therapeutics for cancer treatment alongside RNA therapeutics, anticancer agents, and inhibitors." (PMID 37296273, 2023). "Finally, albumin is widely applied in clinical practice as a marker reflecting the nutritional status of cancer patients." (PMID 37851510, 2023). "As the main component of plasma protein, ALb can reflect the nutritional status of patients, and it has also been widely used as an antidote and transporter in predicting the survival status and disease progression of cancer patients." (PMID 34980151, 2022). "Albumin is catabolized by cancer cells to provide nutrition and energy to the fast-growing tumors." (PMID 35267507, 2022). "Therefore, many studies are currently being performed to develop albumin-based carriers of chemotherapeutics and other albumin-based biomaterials for cancer treatment." (PMID 36430612, 2022). "Moreover, it also inhibits the binding of PTX to endothelial cells and to plasmatic albumin, which can decrease the uptake of this drug by cancer cells and increase PTX-related toxicity." (PMID 35267507, 2022). "Secondly, the decrease in plasma ALB concentration reflects the poor nutritional condition of patients with cancers, which may be related to the chemotherapy resistance of patients." (PMID 34997982, 2022). "In conclusion, following the SARS-CoV-2 lockdown, an improved nutritional status in cancer patients at admission was observed with a decrease in the percentage of weight loss and CRP levels together with an increase in albumin levels compared to oncological patients admitted the previous year." (PMID 35807934, 2022). "Moreover, serum albumin level is an independent prognostic factor in several cancers, including GI malignancies." (PMID 36449698, 2022). "Albumin-bound paclitaxel (abPTX) has been widely used in cancer treatment." (PMID 35244505, 2022). "Vincristine sulphate liposome, doxorubicin hydrochloride liposome, irinotecan hydrochloride liposome, paclitaxel nanodispersion injection concentrate, docetaxel nanoparticles, and paclitaxel albumin stabilised nanoparticle formulation have all been approved by the FDA for cancer therapeutics." (PMID 35684498, 2022). "Studies have shown that serum albumin is related to the prognosis of cancer patients." (PMID 35501704, 2022). "Low serum albumin at diagnosis has been identified as a simple prognostic factor in some cancers including non-Hodgkin's lymphoma (NHL) which comprises more than 50% of all AIDS-defining cancers." (PMID 35717275, 2022). "Albumin is a response to the body's nutritional level, and cancer patients may have worse protein synthesis, increased energy consumption, and a slower recovery, which may explain the longer hospitalization duration compared with noncancer patients." (PMID 36033814, 2022). "By using a well-characterized cancer cell line as a homogenous hepatocyte population, we also demonstrate that an approximate 10% reduction in oxygen triggers translocation of Hif1α to the nucleus and reduces albumin production." (PMID 36496994, 2022). "Furthermore, serum pre-albumin is an important biomarker for assessing the nutritional status of cancer patients." (PMID 35033080, 2022). "Therefore, serum albumin has become a general indicator for predicting the survival rate of various cancers." (PMID 36242047, 2022). "We also found that pretreatment serum albumin could strongly predict patient outcomes after ICB treatment across most cancer types." (PMID 35393553, 2022). "Albumin infusions have been inappropriately prescribed in most patients with cancer." (PMID 36286592, 2022). "Therefore, patterns of change in serum albumin should be interpreted cautiously when predicting the outcomes of critically ill patients with cancer." (PMID 35672868, 2022).
cancer (continued). "Since albumin instability may reduce its prognostic predictive ability in cancer patients, we chose CRP-based mGNRI to construct the prognostic score in this study." (PMID 35433784, 2022). "Importantly, we and others revealed that GAS6–AXL-induced macropinocytic uptake of albumin and cell debris improves the survival of cancer cells under nutrient-deprived conditions." (PMID 35622156, 2022). "Recently, the combination of hemoglobin, albumin, lymphocytes, and platelets (HALP) has been suggested to be a favorable risk predictor of patient survival in several solid tumors, including gastric, colorectal, pancreatic, renal, and bladder cancers." (PMID 35020581, 2022). "Further, other albumin-based drugs have already been approved for the treatment of cancer." (PMID 35416106, 2022). "The logistic regression showed that besides old age, extreme BMI, low preoperative albumin or hemoglobin level, Intraperitoneal surgery, cancer or major surgery, intraoperative hypotension, and colloid infusion were all risk factors, while intraoperative dexmedetomidine was a protective factor." (PMID 35690725, 2022). "Albumin, conversely, represents not only a nutritional indicator, but is similarly involved in the anti-inflammatory response and is utilized as a prognostic predictor of cancer survival, in addition to being considered as a potential cancer drug carrier." (PMID 36295649, 2022). "Intrahepatic obstruction (OR=5.69; P=0.023), stage IV cancer (OR=3.01; P=0.001), pre-endoscopic serum albumin (OR=0.48; P=0.001), TB improvement within 2 weeks after stenting (OR=0.57; P=0.036), and chemotherapy after ERCP (OR=0.11; P<0.001) were associated with 90-day mortality after stenting." (PMID 36147905, 2022). "Low albumin levels and lymphocyte counts reflect systemic inflammation in cancer patients." (PMID 34546503, 2022). "Nab paclitaxel is a good example of nanotechnology in cancer treatment, which combined paclitaxel with albumin protein to assemble into nanostructure, improving the water solubility of paclitaxel and avoiding the severe immune response caused by the addition of castor oil." (PMID 35800328, 2022). "Thus, we conclude that the presence of albumin is in some way required to mediate the observed benefit of contraction-derived myokines on cancer cell growth." (PMID 36388131, 2022). "Recently, several studies have shown that low serum albumin is a risk factor for malignant tumor prognosis, although it alone is not sufficient and accurate to predict the final outcome in cancer patients." (PMID 35495910, 2022). "Inflammation-related parameters, including neutrophil-lymphocyte ratio (NLR), monocyte-lymphocyte ratio (MLR), platelet-lymphocyte ratio (PLR), and C-reactive protein/albumin ratio (CRP/Alb), are associated with tumorigenesis and development and serve as independent prognostic factors for cancer." (PMID 36338698, 2022). "Thus, SIS, which is based on LMR and serum albumin levels, can be used to predict the prognosis of cancer." (PMID 36221349, 2022). "Similarly, ΔS-Cys-Albumin in K2EDTA plasma was higher in CVD patients than in the cancer-free control donors." (PMID 36182099, 2022). "Binding to albumin significantly reduces its availability to cancer cells, which may necessitate the use of relatively high doses." (PMID 35215347, 2022). "In particular, the mGPS, which utilises normal reference value cut-offs for albumin (≥35 g/l) and CRP (≤10 U/l), has been extensively studied and is associated with survival, quality of life, weight loss, and response to treatment in patients with cancer." (PMID 35398717, 2022). "Colorectal and breast cancers are among the less aggressive cancer types and patients often do not exhibit conventional criteria for malnutrition such as low serum albumin, BMI, or weight loss." (PMID 35276977, 2022).
cancer (continued). "As blood tests are regularly performed prior to cancer therapy and serum albumin values are usually included in such routine blood analyses, albumin could be easily obtained and would be widely available." (PMID 35052870, 2022). "Patients with poor nutritional conditions tend to have a poor immune environment, but low serum albumin does not correlate with protein‐energy malnutrition, and it indicates a high metabolic risk and prediction of cancer morbidity and mortality." (PMID 35297197, 2022). "Low serum albumin correlates with poor prognosis and worsened survival among patients with cancers." (PMID 35392843, 2022). "While in the clinic the type of formulation largely depends on the type of cancer [reviewed in], a recent study indicates that nanoparticle albumin-bound paclitaxel readily accumulates in DRG, but is also cleared faster than Cremophor EL paclitaxel (such as used in this study)." (PMID 35250568, 2022). "The reason for the prognostic role of SIS in cancer is largely unclear, and previous studies proposed that it may be elucidated by the role of lymphocyte, monocyte, and ALB." (PMID 36313652, 2022). "A Chi-square test on arches’ links showed that radiotherapy and cancer type were not linked to nutrition (and albumin)." (PMID 36292299, 2022). "In addition, accumulating studies identify preoperative level of serum albumin (ALB) as a prognostic factor for cancer." (PMID 36313652, 2022). "Additionally, an increased vasopermeability in cancer patients results in a higher albumin escape into the extracellular compartment." (PMID 35052870, 2022). "The modified Glasgow Prognostic Score (mGPS) is a combination of C-reactive protein (CRP) and albumin, reflecting the inflammation and nutritional status of patients, and has an independent prognostic value for patients with various cancers, such as liver, lung, and colon cancer." (PMID 36362488, 2022). "Albumin-alkaline phosphatase ratio (AAPR) has been demonstrated to be a prognostic predictor for several cancers, but its predictive value for GBC patients remains unknown." (PMID 36685104, 2022). "In the regression analysis, low appetite was significantly associated with low albumin in men β –0.57 (95% CI: −0.79, −0.36), but not in women, after adjustments for age, cancer type, cancer treatment and socioeconomic status." (PMID 35629338, 2022). "As a result, sesamol-loaded albumin nanoparticles may be considered a viable and potentially clinically applicable nano-based platform for the treatment of cancer and inflammatory illnesses in the future." (PMID 35745652, 2022). "GNRI is an objective and simple screening tool that stands out as a powerful prognostic factor in certain malignancies, but BMI and serum albumin levels by themselves are not strongly associated with the prognosis of cancer patients." (PMID 36061883, 2022). "Indeed, lower serum ALB levels are closely related to systemic inflammation response in cancer patients." (PMID 36531036, 2022). "It is speculated that FCGRT regulates cancer metabolism through the engagement of FcRn with albumin transport." (PMID 36339597, 2022). "Recently, albumin-based nanocarriers have been reported as efficient DDS for cancer therapy." (PMID 35203695, 2022). "The prognostic value of serum albumin has already been shown for different cancer entities." (PMID 35052870, 2022). "Fewer proteins (14 up and 9 down) were significantly dysregulated at 24 hpi and these also fit into two IPA-predicted networks: the amino acid metabolism, increased albumin levels, and molecular transport network and the cancer, hematological disease, and immunological disease network." (PMID 36299731, 2022). "A growing number of studies have implicated chronic inflammation in cancer oncogenesis and development, and several inflammatory parameters, including: neutrophils, lymphocytes, platelets, monocytes, and albumin have been reported to aid in the diagnosis of a variety of cancers." (PMID 36483052, 2022).